TNF (tumor necrosis factor)
Diseases named in the same sentence as TNF in open-access papers (continued):
Sharing a sentence is not in itself a finding about the gene and the disease.
abortion (34 papers, 2005 to 2025). the ending of pregnancy by removing a fetus or embryo before it can survive outside the uterus. "Excessive levels of TNF-alpha have been implicated in complications during pregnancy, such as recurrent spontaneous abortion and recurrent implantation failure." (PMID 41232126, 2025). "The administration of single low doses of the inflammatory Th1 cytokines TNFα and IFNγ into pregnant mice causes abortions while the injection of anti-TNFα antibodies reduces abortion rates in an immunologically-driven mouse abortion model." (PMID 34394125, 2021). "For TNF‐α it was shown that increased levels were associated with abortion in mice and there is evidence that treatment with anti‐TNF‐α antibodies may have a beneficial effect on IVF rates and improves life birth rates in women with recurrent abortions." (PMID 39460389, 2024). "Consequently, NK cells produce TNF and target trophoblast cells to cause spontaneous abortion during pregnancy." (PMID 38131979, 2023). "The levels of inflammatory cytokines such as TNF-α or the presence of NK cells could also be associated with abortion resulting from C. abortus infection." (PMID 37375536, 2023). "Elevated TNF-α expression is associated with spontaneous abortion and preterm delivery." (PMID 33374185, 2020). "The level of TNFα in the amniotic fluid was 1.5 fold more in unvaccinated pregnant infected mice which could be a possible cause of increased incidence of abortion and fetal death in the unvaccinated mice." (PMID 20161765, 2010). "However, TNF-α 238 GG genotype was present more frequently in patients with unexplained recurrent spontaneous abortion (URSA), suggesting that it could be a risk factor in Chinese RSA patients." (PMID 33838693, 2021). "They found IFN-γ, TNF-α, IL-2, IL-6 and IL-17A cytokines were significantly increased in spontaneous abortion ((SA) group and recurrent miscarriage (RM) group (Ctinfected) versus controls." (PMID 35392343, 2021). "We also showed that the expression of IFN-γ and TNF-α were dramatically increased in decidual tissues from LPS-induced abortion model." (PMID 34399700, 2021). "We found the serum levels of IL-10, a representation of Th1 cytokines, were significantly lower in abortion-prone mice model whereas the serum level of TNF-α and INF-γ, a representation of Th2 cytokines, were significantly higher." (PMID 33763083, 2021). "The hypothalamic–pituitary–adrenal axis is stimulated via the release of corticotrophin-releasing hormone by TNF-α, and the corticotrophin hormones have a role in the induction of abortion, especially with increased levels of TNF-α." (PMID 32784541, 2020). "We have observed elevated expression of pro-inflammatory mediators such as TNF-α in the placentas of sheep that experience early abortion as a result of C. abortus infection and have reproduced these findings in infected AH-1 trophoblast cells." (PMID 30687304, 2018). "The results showed that the mean plasma level of IL-1β, IL-6 and TNF-α in repeated abortion were markedly higher than those in control group." (PMID 30061639, 2018). "Murine studies demonstrate that administration of pro-inflammatory cytokines (i.e. TNFα, IFN, IL-2) into pregnant mice causes increased abortion." (PMID 28636613, 2017). "We have shown in this study that the natural Th2 bias of pregnancy is not altered by the vaccine strain whereas the wild type Salmonella induces a Th1 mediated immune response with increased Th1 cytokines (IFNγ, TNFα) leading to abortion." (PMID 20161765, 2010). "Predominant Th1-type immunity has been observed in recurrent spontaneous abortion and, more precisely, circulating levels of TNF-α and IFN-γ (Th1 cytokines) were reported to be higher in patients with a subsequent miscarriage than in women with a successful pregnancy." (PMID 38157038, 2023).
abortion (continued). "On the other hand, there is a strong correlation between spontaneous abortion and increased production of proinflammatory factors, such as cytokines TNF-α and IFN-γ, and conversely, a reduction in the anti-inflammatory cytokine IL-10 is also associated with spontaneous abortion." (PMID 37760110, 2023). "Supporting this hypothesis, a previous study documented that overexpression of TNF-α, reduce MMP-2 and MMP-9, while an aggravation of the severity of abortion in rats further prompted TNF-α expression that sequentially decreased MMP-2 and MMP-9 levels." (PMID 35622593, 2022). "Similarly to the data obtained from our analysis, previous studies described increased serum levels of TNF-α and IL-6 levels in patients with spontaneous abortion than in women with normal pregnancies." (PMID 35955896, 2022). "While it decreases the levels of proinflammatory cytokines such as progesterone, IL-6, and TNF-α, which are frequently used in the treatment of threatened abortion, it increases the levels of the anti-inflammatory cytokine IL-10 in proportion to the administered dose." (PMID 34909296, 2021). "Therefore, if these findings with the mouse model hold true in cattle, VceC and other B. abortus virulence factors may serve as transmission factors, eliciting a TNF-α response that drives placental inflammation and abortion." (PMID 35100011, 2022). "For instance, demonstrated that levels of IL5, IL6, IL1-ß, TNF-α, TLR4, and Tollip were significantly up-regulated in ewes affected with abortion than in resistant ones, while SOD and CAT gene patterns elicited an opposite trend." (PMID 40872670, 2025). "Furthermore, TNF can inhibit trophoblast invasion, and one report showed that inhibiting its activity may improve live birth rates in women with recurrent spontaneous abortion." (PMID 35682747, 2022). "Experimentally infected mares expressed more IL-6, IL-8, IL-1β, and TNF-α mRNA in the cervical star region and produced high concentrations of PGE2 and PGF2α in allantoic fluid, leading to abortion or birth of a precociously mature foal." (PMID 23390521, 2013). "Consequently, the presence of higher TNF-α levels in the DD placentae is not surprising, demonstrating a relationship between this cytokine and abortion in sheep." (PMID 37375536, 2023).
bone cancer (34 papers, 2010 to 2026). A primary or metastatic malignant neoplasm affecting the bone or articular cartilage. "In a mouse femur model where MC57G fibrosarcoma cells were injected to induce bone cancer, epigallocatechin gallate lessened the neuroinflammation and pain behavior caused by bone cancer through suppressing TNF-α expression in the spinal cord." (PMID 41267743, 2025). "CXCL12/CXCR4 signaling pathway activates sensitized neurons, astrocytes and microglia through mitogen-activated protein kinase (MAPK), promotes the release of inflammatory factors, such as IL(interleukin) and TNF, and causes persistent bone cancer pain." (PMID 39654896, 2024). "The pro-inflammatory interleukin (IL)-1β, IL-6 and tumor necrosis factor (TNF)-α are associated with nociception in animal models of bone cancer." (PMID 30266081, 2018). "In terms of spinal effects, EGCG decreases TNF-α expression in the spinal cord in mouse models of bone cancer-caused pain and reduces glial cell activation via inhibition of fatty acid synthase (FASN), Ras homologue gene family member A (RhoA), and TNF-α in a model of spinal cord injury (SCI)." (PMID 32050623, 2020). "Mechanisms underlying L-THP-induced attenuation of bone cancer pain may be partially through inhibiting microglial cells activation, as well as proinflammatory cytokines TNF-α and IL-18 releasing, in spinal cord." (PMID 26819501, 2015). "In addition, a previous study suggests that IL-33 plays an essential role in bone cancer pain, and its actions might be associated with inducing spinal upregulation of IL-1β and TNF-α." (PMID 29329586, 2018). "XPro1595, a TNF-α inhibitor, dose-dependently reduced mechanical allodynia in bone cancer rats, accompanied by decreased astrocyte and microglia activation and diminished pro-inflammatory cytokine production." (PMID 38940936, 2024). "It was found that the expression of TNF-α in serum of mice with bone cancer pain was significantly higher than that of normal mice (P < 0.01)." (PMID 37652923, 2023). "Among them, BDNF and TNF produced in bone tumor metastasis metabolism-α, MCP-1 and CCR2 can activate TRPA1." (PMID 35295475, 2021). "During tumor growth and development of bone cancer pain, certain proinflammatory cytokines such as TNF-α and IL-1β are activated and released from the astrocytes and microglial cells and contribute to bone cancer pain." (PMID 26989332, 2016). "It is possible that inhibition of IL-1A, as well as downstream effects on other cytokines including TNF alpha, contribute to the reduced of growth of both subcutaneous and bone tumours following administration of anakinra." (PMID 27765923, 2016). "Our results indicate that XAT decoction can effectively alleviate bone cancer pain, suppress morphine-induced adverse actions, reduce the proinflammatory cytokines IL-1β and TNF-α, and increase the endogenous anti-inflammatory cytokine IL-10." (PMID 26617438, 2015). "Intraperitoneal injection of thalidomide (50 mg/kg), started at day 1 after surgery and once daily thereafter until day 7, attenuated bone cancer-evoked mechanical allodynia and thermal hyperalgesia as well as the up-regulation of TNF-α in the spinal cord." (PMID 20923560, 2010). "Our results provide further support for the use of TNF-α antagonism as a means of reducing cancer pain, particularly bone cancer pain." (PMID 20923560, 2010). "We found that TNF-α synthesis inhibitor thalidomide decreased the bone cancer related pain behaviors as well as the up-regulation of TNF-α in the spinal cord." (PMID 20923560, 2010). "In summary, the present study demonstrated that bone cancer induced mechanical allodynia and thermal hyperalgesia as well as the up-regulation of TNF-α in the spinal cord." (PMID 20923560, 2010). "Similar to TNF-α, IL-1β is expressed in both microglia and astrocytes and is upregulated in astrocytes in various chronic pain conditions, including inflammatory pain, neuropathic pain, and bone cancer pain." (PMID 40349773, 2025).
bone cancer (continued). "By effectively suppressing the activity of tumor necrosis factor (TNF), it effectively hampers the development and proliferation of bone cells, hence mitigating the potential danger of developing bone cancer (Zhu, Arsovska, & Kozovska, 2020; Zhu, Chen, & Li, 2020)." (PMID 38628211, 2024). "The metabolism of bone tumors is extraordinarily complex and involves many signaling pathways and processes, including the tumor necrosis factor (TNF) signaling pathway, which consists of TNF factors and the TNF receptors that belong to the TNF receptor superfamily (TNFRSF)." (PMID 35847045, 2022). "Therefore, in the present study, we investigated the effect of thalidomide on bone cancer-induced hyperalgesia and up-regulated expression of spinal TNF-α in a mouse model." (PMID 20923560, 2010). "Hence, further studies with intrathecal TNF-α receptor antagonists are necessary to demonstrate the potential role of TNF-α in the development of bone cancer pain." (PMID 20923560, 2010). "Our data also suggest a role of spinal TNF-α in the development of bone cancer pain." (PMID 20923560, 2010). "We may not have selected the optimal dose of thalidomide or, more likely, apart from TNF-α, there may be involvement of additional factors in bone cancer pain." (PMID 20923560, 2010). "In the present study, we provide additional evidence that bone cancer-induced TNF-α up-regulation may be responsible for the development of mechanical allodynia and thermal hyperalgesia." (PMID 20923560, 2010). "The present study further demonstrated that spinal TNF-α was significantly up-regulated in tumor-bearing mice and intraperitoneal injection of thalidomide decreased spinal TNF-α expression as well as bone cancer-induced mechanical allodynia and thermal hyperalgesia." (PMID 20923560, 2010). "Studies have demonstrated that astrocytes and microglial cells, which act as parts of the innate immune system, become active in the status of bone cancer and release various substances, including the proinflammatory cytokines IL-1β and TNF-α, which could evoke hyperalgesia and allodynia." (PMID 26617438, 2015). "We also provide evidence that spinal TNF-α may participate in the development of bone cancer pain." (PMID 20923560, 2010). "Recent evidence suggests that TNF-α may affect bone cancer-related hyperalgesia." (PMID 20923560, 2010). "Compared to that of control tumors, TAMs in ASH1L-depleted bone tumors showed significant elevation in inflammation pathways, including IFN signaling, TNF signaling, IL-1/2 signaling, cGAS-STING, and antigen processing and presentation pathway." (PMID 40394007, 2025). "In bone cancer, OT alleviates bone cancer pain by inhibiting the upregulation of TLR4, TNFα, and IL-1β in the spinal cord." (PMID 39290327, 2024). "Injection of PTX (TNF-α synthesis inhibitor, pentoxifylline) and TRPA1 modulation attenuated mechanical and thermal hypersensitivity induced by bone cancer." (PMID 38940936, 2024). "Several pro-inflammatory cytokines (IL-1β, TNFα, IL-6, and TGFβ) and inflammatory mediators (CGRP) are increased in the DRG in response to bone cancer and fracture." (PMID 27199772, 2016). "Increased expression of spinal SP, CGRP, and other inflammatory mediators (TNF, IL-1, IL-6, CCL2, and nerve growth factor) are observed in the spinal cord of rats with fracture-induced and bone cancer-induced pain." (PMID 27199772, 2016). "One of the neuron-to-glial activation signals has proposed that proinflammatory cytokines, such as IL-1, IL-6, and TNF-α, were released via the microglial TLR4 receptor in a rat model of bone cancer pain." (PMID 26556957, 2015). "For instance, the up-regulation of tumour necrosis factor-α (TNF-α) and interleukin-6 (IL-6) in bone metastases may activate TRPA1 in the sensory neurons of bone cancer rats and contribute to CIBP." (PMID 39940997, 2025).
bone cancer (continued). "Both TNF-α and IL-17 play an important role in the formation of bone cancer pain, but the mechanism of BCP has not been fully elucidated because of its complex mechanism." (PMID 37652923, 2023). "Both inflammatory cytokines TNF (α) and IL6 regulate bone cancer pain via TRPA1, but no data have proven the relationship between TRPA1 and tumours." (PMID 39770499, 2024).
brucellosis (34 papers, 2007 to 2026). Brucellosis is a bacterial infection that spreads from animals to people via unpasteurized dairy products or by exposure to contaminated animal products or infected animals. "In our univariate analysis, IL-4, IL-6, IL-10, IL-17, IFN-γ, and TNF-α were risk factors for brucellosis." (PMID 32381058, 2020). "The aim of the present study was to investigate the relationship between TNF-α, IL-12, and IL-13 gene polymorphisms and predisposition to brucellosis." (PMID 31818255, 2019). "The aim of the present study was to investigated the association between TNF-α)- 238 G/A), IL-12 (+ 1188 A/C), and IL-13 (− 1512 A/C and − 1112 C/T) gene polymorphisms and their serum levels and susceptibility to brucellosis comparison to healthy subjects." (PMID 31818255, 2019). "Studies in humans reported that monocytes and dendritic cells from patients with brucellosis released lower levels of TNF in response to external stimuli compared to healthy controls." (PMID 40406273, 2025). "We found that IL-4, IL-6, IL-10, IL-17, IFN-γ, and TNF-α levels were higher in those with brucellosis than in controls." (PMID 32381058, 2020). "Levels of IL-4, IL-6, IL-10, IL-17, IFN-γ, and TNF-α were all significantly higher in those with brucellosis than in the control group (all P < 0.05)." (PMID 32381058, 2020). "We found that IL-4, IL-6, IL-10, IL-17, IFN-γ, and TNF-α levels were higher in patients with brucellosis than healthy controls, indicating a strong immune response was occurring." (PMID 32381058, 2020). "We found that IL-4, IL-6, IL-10, IL-17, IFN-γ, and TNF-α levels were higher in those with brucellosis than in controls (P < 0.05)." (PMID 32381058, 2020). "The mean serum TNF-α level of patients with brucellosis (15.20 ± 60.37 pg/ml) compared with the controls groups (1.34 ± 1.41 pg/ml)." (PMID 31818255, 2019). "In this study, there were significant differences in IFN-γ and TNF-α levels between the brucellosis patients and healthy subjects." (PMID 31686983, 2019). "The mean serum levels of IFN-γ and TNF-α and the frequency of Th1 cells were significantly higher in the brucellosis patients in comparison with the healthy subjects (p < 0.05)." (PMID 31686983, 2019). "The previous study have reported significant differences between patients with brucellosis and controls in GG/GG genotypes of TNF-α (− 238 G/A,-308 G/A) and G allele of TNF-α (− 238 G/A) locations." (PMID 31818255, 2019). "Conversely, 3-MA treatment that inhibited autophagy led to elevated expression of TNF-α, IL-6, IL-1β, and IL-10 than those from untreated monocytes from brucellosis patients." (PMID 28659924, 2017). "TNF-α is pro-inflammatory and triggers apoptosis in infected cells by activating caspases, this being the principal defense mechanism against brucellosis in cattle." (PMID 21637417, 2010). "Notably, the chronic form of bovine brucellosis was associated with increased expression of IFN-γ, IL-1β, IL-6 and iNOS genes, along with reduced expression of TNF-α, IL-4 and IL-12p40 genes." (PMID 39825331, 2025). "In agreement, significant increases in TNF-α in the acute phase of brucellosis cases were reported." (PMID 39825331, 2025). "Treatment with APS could resist the infection of the pathogen Brucella and alleviate the symptoms of mice with brucellosis by activating the macrophages and upregulating the production of TNF-α, IL-12, and IFN-γ." (PMID 40109962, 2025). "In human brucellosis, higher TNF-α levels have been reported in patients with brucellosis." (PMID 38794208, 2024). "Genes known to be highly associated with brucellosis contain multiple SNP sites, such as TGF-β, IFN-γ, TNF-α, IL-15, and TNF-α." (PMID 34306007, 2021). "In this study, we examined the relationship between brucellosis and cytokine levels, and found IL-4, IL-6, IL-10, IL-17, IFN-γ, and TNF-α were all risk factors for brucellosis, although only IL-6 and INF-γ were independent risk factors for the severity of brucellosis." (PMID 32381058, 2020).